TRPM2 (transient receptor potential cation channel subfamily M member 2)
Diseases named in the same sentence as TRPM2 in open-access papers (continued):
Sharing a sentence is not in itself a finding about the gene and the disease.
hepatic disease (2 papers, 2015 to 2021). "Curcumin, as a potential pharmacological agent for the clinical treatment of liver disease or injury via inhibition of TRPM2, offers two other advantages." (PMID 34439491, 2021). "As will further investigation of the balance between the detrimental and beneficial pathways initiated by TRPM2 channels in ROS-mediated liver diseases." (PMID 34439491, 2021). "The aim of this review is to summarise the current knowledge of the roles of TRPM2 channels and intracellular Ca2+ in mediating ROS-initiated liver injury and the progression of liver disease and liver injury to end-stage liver disease or liver failure." (PMID 34439491, 2021). "Based on the results of studies conducted so far, TRPM2 channels may offer a suitable pharmacological target for the prevention and/or management of ROS-induced liver disease." (PMID 34439491, 2021). "However, considerable further studies are needed to define the mechanism by which curcumin inhibits TRPM2 and to test its potential clinical usefulness for the treatment of liver diseases." (PMID 34439491, 2021). "However, it is important to note that the TRPM2 channels in some other organs, such as the pancreas and brain, and in white blood cells, also play important indirect roles in the progression of ROS-mediated liver diseases, such as diabetes." (PMID 34439491, 2021). "Given the importance of ROS in liver diseases and of TRPM2 and intracellular Ca2+ in mediating ROS-induced cell injury and death in other cell types and organs, it is somewhat surprising that there have so far been relatively few studies of the role of TRPM2 in oxidative stress in liver diseases." (PMID 34439491, 2021).
infarction (2 papers, 2022 to 2023). A localised pathological necrosis of tissue resulting from obstruction of the blood supply usually by a thrombus, an embolus, or vascular torsion. "A previous study showed that exposure of TRPM2 knockout mice to myocardial IR led to less infarction than that in WT mice." (PMID 37275121, 2023).
insulinoma (2 papers, 2016 to 2020). "In rat insulinoma cell lines, H2O2 and TNFα cause cell death, which can be inhibited by treatment with antisense-TRPM2." (PMID 32168890, 2020). "Other rodent insulinoma cells that express TRPM2 are the INS-1E cells, the RIN-5F cells, and theHIT-T15 cells." (PMID 32168890, 2020).
juvenile myoclonic epilepsy (2 papers, 2020 to 2023). "TRPM2 may be a channel protein of interest in juvenile myoclonic epilepsy as EFHC1, the candidate gene for this disease, potentiates TRPM2 in ROS-mediated neuronal death." (PMID 36902145, 2023). "TRPM2 is reported to have molecular and functional interaction with EF-hand motif-containing protein (EFHC1), mutation in which causes juvenile myoclonic epilepsy (JME) via neuronal apoptosis." (PMID 32963700, 2020).
kidney injury (2 papers, 2023 to 2025). Trauma to the kidney. "TRPM2 was an important moderator in ischemic acute kidney injury, and the deletion of TRPM2 and pharmacological blockade of TRPM2 could produce protection in the kidney." (PMID 41009007, 2025).
lupus nephritis (2 papers, 2023 to 2025). Glomerulonephritis in the context of systemic lupus erythematosus. "Another study reported that the TRPM2–Ca2+–NLRP3 axis has been implicated in lupus nephritis and periodontitis-associated bone defects as a common regulatory node for inflammatory–osteogenic imbalance." (PMID 41293090, 2025).
memory impairment (2 papers, 2014 to 2019). "We thus evaluated whether TRPM2 deficiency can also protect against transient ischemia-induced memory impairment." (PMID 25429618, 2014).
multiple sclerosis (2 papers, 2024 to 2025). A progressive autoimmune disorder affecting the central nervous system resulting in demyelination. "For instance, reduced demyelination, synapse loss, microglial activation, and pro‐inflammatory cytokines production were noted on TRPM2‐knockout mice induced to a model of multiple sclerosis." (PMID 40665621, 2025). "In an animal model of multiple sclerosis, TRPM2-KO or pharmacological inhibition of TRPM2 inhibits the progression of the disease." (PMID 39329114, 2024).
myeloid leukemia (2 papers, 2020 to 2022). A clonal proliferation of myeloid cells and their precursors in the bone marrow, peripheral blood, and spleen. "Targeting TRPM2 may represent a novel therapeutic approach to inhibit myeloid leukemia growth and enhance susceptibility to chemotherapeutic agents through multiple pathways." (PMID 32312983, 2020). "Determination of the role of TRPM2 in doxorubicin sensitivity of the myeloid leukemia cell line U937 similarly demonstrated reduced FOXM1, E2F1, and expression of proteins involved in cell cycle and DNA damage response in cells with TRPM2 deletion." (PMID 35428820, 2022). "Downregulation of the same cell cycle and DNA repair regulators was found in U937 myeloid leukemia cells in which TRPM2 was deleted." (PMID 35428820, 2022). "The work presented here demonstrates the important role of TRPM2 in regulation of mitochondrial function, ROS production, bioenergetics, and autophagy in proliferation and survival of myeloid leukemia." (PMID 32312983, 2020). "The second major finding here is that mitochondrial function is significantly decreased and ROS increased in TRPM2-depleted human myeloid leukemia cells, particularly after doxorubicin exposure." (PMID 32312983, 2020). "The role of TRPM2 in AML proliferation and chemotherapy sensitivity was examined here using myeloid leukemia cells in which TRPM2 was depleted." (PMID 32312983, 2020).
oral squamous cell carcinoma (2 papers, 2016 to 2021). "TRPM2-expression was upregulated in oral squamous cell carcinoma (OrSCC) tissue." (PMID 36046118, 2021).
pancreatic adenocarcinoma (2 papers, 2022). "In addition to being activated by their activators, TRPM2, TRPM4, and TRPM5 can also be triggered by the influx of Ca2+ to participate in membrane depolarization, and TRPM2, TRPM7, and TRPM8 are involved in the progression of pancreatic adenocarcinoma." (PMID 35573736, 2022).
peripheral nerve injury (2 papers, 2013 to 2016). Injury to a peripheral nerve. "In the neuropathic pain models induced by peripheral nerve injury, the deletion of TRPM2 channel attenuates the neutrophil infiltration through the activation of spinal microglia and the production of chemokine ligand-2 from macrophages around the damaged peripheral nerve." (PMID 26942016, 2016).
sarcoma (2 papers, 2021 to 2022). A usually aggressive malignant neoplasm of the soft tissue or bone. "In this report, a new isoform of TRPM2, TRPM2-S was identified and validated from the TCGA database and our REtroperitoneal SArcoma Registry (RESAR) cohort." (PMID 36008839, 2022).
tongue cancer (2 papers, 2016 to 2018). A malignant neoplasm affecting the tongue. "Through analysis of 23 human tongue carcinoma samples, 22 specimens showed an overexpression of TRPM2, and one weakly positive TRPM2 staining was observed." (PMID 28008929, 2016). "To further explore the role of TRPM2 in tongue carcinoma, we inhibited the expression of TRPM2 by transfection with shRNATRPM2 in SCC-9 cells." (PMID 28008929, 2016). "Consistent with it, the high expression levels of TRPM2 protein were also observed in tongue carcinoma samples by Western Blot test compared with the control group." (PMID 28008929, 2016). "All these results suggested that the expression of TRPM2 was elevated in human carcinoma of tongue specimens." (PMID 28008929, 2016). "In the tongue cancer cells, a number of TRPM2 was observed in the nuclei, though the membrane TRPM2 still performed its function since ADPR-induced current was recorded in SCC-9 cell." (PMID 28008929, 2016). "All these data suggested that overexpressed TRPM2 tongue carcinoma might be involved in the survival and migration of the cancer cell." (PMID 28008929, 2016). "Expression of TRPM2 protein was detected in the nuclei of the human tongue carcinoma samples." (PMID 28008929, 2016). "Thus we also observed the localization of TRPM2 in tongue carcinoma." (PMID 28008929, 2016). "In the human tongue specimens of carcinoma and the tongue carcinoma SCC cell lines, we observed the enhanced expression of TRPM2." (PMID 28008929, 2016). "All these data suggest that TRPM2 is essential for the survival and migration of SCC cancer cells and may be a potential target for the selective treatment of tongue cancer." (PMID 28008929, 2016). "Moreover, we also observed the TRPM2 expression in the cytoplasm preparations in the human tongue carcinoma samples, but not in normal samples." (PMID 28008929, 2016).
abscesses (1 paper, 2020). "Similar results were observed in livers of mice infected with L. monocytogenes, where Trpm2−/− mice had a larger number of abscesses compared to WT mice." (PMID 32117251, 2020). "At 72 hpi Trpm2−/− mice showed a large number of abscesses in the liver." (PMID 32117251, 2020). "Similar results were observed in the liver, where, Trpm2−/− mice showed numerous abscesses, however, the absence of neutrophils in Trpm2−/− mice reduced the number of abscesses in the liver." (PMID 32117251, 2020).
acute leukemia (1 paper, 2020). A clonal (malignant) hematopoietic disorder with an acute onset, affecting the bone marrow and the peripheral blood. "We speculate that correct signaling between TRPM2 and PARPs is essential for physiology, and its loss may affect the development of acute leukemia." (PMID 32423430, 2020). "Many studies indicate that TRPM2 is an ion channel that is modulated, and that can be altered to increase apoptosis in cancer cells including acute leukemia cells." (PMID 32423430, 2020). "Based on the conducted studies, we noted that the bone marrow and blood cell samples of the patients with acute leukemia showed statistically significantly lower mean TRPM2 gene expression compared to the normal bone marrow." (PMID 32423430, 2020).
acute lymphoblastic leukemia (1 paper, 2022). Leukemia with an acute onset, characterized by the presence of lymphoblasts in the bone marrow and the peripheral blood. "TRPV1, TRPV6 and TRPM2 contribute to the growth of cells derived from acute lymphoblastic leukemia (ALL)." (PMID 36330491, 2022).
allergic asthma (1 paper, 2013). A asthma with a basis in a pathological type I hypersensitivity reaction. "Using TRPM2 deficient (TRPM2-/-) mice, we investigated whether the TRPM2 ion channel, which mediates calcium (Ca2+) influx and lysosomal Ca2+ release, plays a role in the pathophysiology of severe allergic asthma in mouse." (PMID 23631390, 2013). "Together, these data indicate that the TRPM2 channel does not regulate the bronchoalveolar inflammatory cell infiltration in an OVA-induced severe allergic asthma mouse model." (PMID 23631390, 2013). "The absence of TRPM2 channels has no obvious effect on major etiologic markers of severe allergic asthma in this mouse model." (PMID 23631390, 2013). "In summary, these data indicate that TRPM2 channels are not involved in the pathophysiology of OVA-induced severe allergic asthma in our mouse model." (PMID 23631390, 2013). "TRPM2 is not required for airway inflammation in OVA-induced severe allergic asthma in mice." (PMID 23631390, 2013).
anxiety disorder (1 paper, 2025). A category of psychiatric disorders which are characterized by anxious feelings or fear often accompanied by physical symptoms associated with anxiety. "Given the enhanced extinction observed in Trpm2−/− mice, TRPM2 inhibition may be a promising avenue for facilitating the extinction of fear memories in patients with PTSD and other anxiety disorders." (PMID 40016847, 2025).
attention deficit-hyperactivity disorder (1 paper, 2020). A disorder characterized by a marked pattern of inattention and/or hyperactivity-impulsivity that is inconsistent with developmental level and clearly interferes with functioning in at least two settings (e.g. at home and at school). "An association between ASD or attention-deficit hyperactivity disorder and TRPM2 has not been reported yet." (PMID 32046066, 2020).
autism (1 paper, 2016). Persistent deficits in social interaction and communication and interaction as well as a markedly restricted repertoire of activity and interest as well as repetitive patterns of behavior. "Our results suggest that TRPM2 or single nucleotide polymorphisms, in TRPM2 may be a new target protein and this gene should be screened to assess its association with autism." (PMID 27499729, 2016).
brain tumors (1 paper, 2023). "The importance of TRPM2, as a potential therapeutic target for brain tumors, in ion channels and pharmacology was reported in a previous study." (PMID 36830651, 2023).
chronic obstructive pulmonary disease (1 paper, 2013). A chronic and progressive lung disorder characterized by the loss of elasticity of the bronchial tree and the air sacs, destruction of the air sacs wall, thickening of the bronchial wall, and mucous accumulation in the bronchial tree. "Yet, a recent publication has suggested no role for TRPM2 channel in chronic obstructive pulmonary disease." (PMID 23631390, 2013).
COVID-19 (1 paper, 2021). A disease caused by infection with severe acute respiratory syndrome coronavirus 2. "Because TRPM2 has a pivotal role in COVID-19 pathogenesis, especially in respiratory failure, TRPM2 inhibitors are potential drugs to be valued for combating SARS-CoV-2 infections in human clinical trials." (PMID 34064039, 2021). "Based on existing evidence, TRPM2 targeting may be an appropriate strategy for combating COVID-19." (PMID 34064039, 2021).
dermatitis (1 paper, 2019). An inflammatory process affecting the skin. "Using a mouse model of radiodermatitis, we showed that the Transient Receptor Potential Melastatin 2 (TRPM2) ion channel plays a significant role in the development of dermatitis following exposure to ionizing radiation." (PMID 30483886, 2019).
diabetic nephropathy (1 paper, 2021). "Clinically, the mRNA levels of TRPM2 were significantly increased in kidney biopsies obtained from human subjects with diabetic nephropathy." (PMID 34845114, 2021). "We explore the protective effect of TRPM2 knockdown on the progression of diabetic nephropathy." (PMID 34845114, 2021).
endometrium adenocarcinoma (1 paper, 2019). An adenocarcinoma arising from the uterine body cavity. "This study compared TRPM2 and TRPM7 ion channel gene expression and immunohistochemical staining in endometrial hyperplasia and endometrium adenocarcinoma." (PMID 30997980, 2019).
Erythema (1 paper, 2019). Redness of the skin, caused by hyperemia of the capillaries in the lower layers of the skin. "At 4 weeks, WT mice developed a pronounced loss of hair along with erythema and desquamation of the epidermis while TRPM2−/− mice had just begun to show signs of hair loss." (PMID 30483886, 2019).
focal segmental glomerulosclerosis (1 paper, 2025). A renal disorder characterized by sclerotic lesions in the glomeruli. "While several TRP channels expressed in the kidney were involved in disease states, such as those implicated in polycystic kidney disease and focal segmental glomerulosclerosis, the role of TRPM2 in kidney physiology or pathophysiology is still unknown." (PMID 41009007, 2025).
Glomerular sclerosis (1 paper, 2021). Accumulation of scar tissue within the glomerulus. "In addition, silencing of TRPM2 attenuated glomerular damage, as shown by HE and PAS staining, and reduced the severity of glomerular sclerosis, tubular damage and interstitial fibrosis as shown by Masson and Sirius staining, in the kidneys of diabetic mice." (PMID 34845114, 2021).
Glucose intolerance (1 paper, 2024). Glucose intolerance (GI) can be defined as dysglycemia that comprises both prediabetes and diabetes. "We hypothesized that TRPM2 on lysosome could be involved in LP-induced inflammasome since TRPM2 has been reported to be expressed on lysosome as well and Trpm2-KO mice are resistant to diet-induced glucose intolerance." (PMID 38953285, 2024).
gouty arthritis (1 paper, 2024). "In an animal model of gout, TRPM2 depletion significantly attenuated MSU-induced inflammation dominated by neutrophil infiltration (Ref." (PMID 38659380, 2024). "In conclusion, TRPV1, TRPM2 and TRPA1 gene knockout or pharmacological inhibition can reduce joint pain and oedema in mice with gouty arthritis." (PMID 38659380, 2024).
Hepatic steatosis (1 paper, 2024). Steatosis is a term used to denote lipid accumulation within hepatocytes. "TRP channels exhibit both pro- and anti-hepatic steatosis activity, evidenced by the observation that loss of TRPC5, TRPV1, and TRPM2 protected, whereas loss of TRPV4 aggravated hepatic steatosis." (PMID 39871879, 2024).
Hyperbilirubinemia (1 paper, 2025). An increased amount of bilirubin in the blood. "TRPM2 is a highly Ca2+‐permeable, non‐selective cation channel expressed in immune cells and neurons, mediating Ca2+ influx that initiates signaling cascades responsible for neuronal excitability and injury associated with hyperbilirubinemia pathology." (PMID 40112213, 2025).
hypertrophy (1 paper, 2025). Hypertrophy is the increase in the volume of an organ or tissue due to the enlargement of its component cells. "Loss of TRPM2 impairs ANP production under β-adrenergic stress, leading to exacerbated cardiac hypertrophy and fibrosis." (PMID 41511308, 2025).
hypospadias (1 paper, 2022). Hypospadias is the displacement of the urethral meatus on the ventrum of the penis. "This was associated with increased mRNA expression of Ca2+ channels important in regulating VSMC Ca2+ influx, specifically CACNA1C (P = 0.03), IP3R (P = 0.007), TRPM2 (P = 0.001), SERCA (P = 0.008), and RyR1 (P = 0.01) in boys with hypospadias vs. controls." (PMID 35567552, 2022).
ileus (1 paper, 2022). Decrease in peristalsis in the absence of a mechanical bowel obstruction. "The genetic deficiency of TRPM2, which is expressed in intestinal macrophages and enteric neurons, prevents the development of ileus (gut manipulation model), suggesting that TRPM2 channels may be involved in the mechanotransduction of ileus development." (PMID 36613619, 2022).
kidney (1 paper, 2025). "However, it was demonstrated that TRPM2 mediated ischemic kidney injury and oxidant stress." (PMID 41009007, 2025).
kidney cancer (1 paper, 2021). Primary or metastatic malignant neoplasm involving the kidney. "Only one article has mentioned that the overexpression of TRPM2 might be used as a diagnostic marker for kidney cancer in terms of sensitivity and specificity, indicating strong diagnostic potential of TRPM2." (PMID 35071322, 2021).
laryngeal carcinoma (1 paper, 2026). Carcinoma that arises from the laryngeal epithelium. "This study investigated the involvement of the transient receptor potential melastatin-2 (TRPM2) channel in the HESP-mediated potentiation of CSP-induced cytotoxicity in human laryngeal carcinoma (Hep-2) cells." (PMID 41683568, 2026).
laryngeal squamous cell carcinoma (1 paper, 2021). A squamous cell carcinoma that arises from the larynx. "Interestingly, introducing long non-coding TRPM2-anti-sense promotes EMT via SOX4 signaling in laryngeal squamous cell carcinoma cell lines, suggesting that the effect of TRPM2 on EMT induction in cancer cells might not be limited to its function as an ion channel." (PMID 34360952, 2021).
mood disorder (1 paper, 2023). A cognitive disorder a disturbance in which the person's mood is hypothesized to be the main underlying feature. "Beyond TRPM2, recent research highlights TRPM3 as a potential player in the development of mood and anxiety disorders, with specific mention of post-partum mood disorders." (PMID 36902145, 2023).
Myocardial fibrosis (1 paper, 2024). "However, TRPM2 knockdown did not attenuate HFD/STZ-induced myocardial fibrosis in the diabetic hearts." (PMID 38308007, 2024).